MIR941-5 (microRNA 941-5)
Gene: MicroRNA gene on chromosome 20 (63,919,868 to 63,919,939, forward strand). Ensembl gene ENSG00000275842.
Homologues: Paralogues in human: MIR941-3 (100% identical), MIR941-2 (22% identical), MIR941-4 (0% identical).